PCIF1 (phosphorylated CTD interacting factor 1)
Diseases named in the same sentence as PCIF1 in open-access papers (continued):
Sharing a sentence is not in itself a finding about the gene and the disease.
head and neck squamous cell carcinoma (2 papers, 2023 to 2024). A squamous cell carcinoma that arises from any of the following anatomic sites: lip and oral cavity, nasal cavity, paranasal sinuses, pharynx, larynx, and salivary glands. "Here, we demonstrated that PCIF1-mediated cap mRNA m6Am modification promoted head and neck squamous cell carcinoma progression both in vitro and in vivo." (PMID 37643007, 2023). "In this study, we found that PCIF1 was overexpressed in head and neck squamous cell carcinoma (HNSCC) cancer tissues and served as a prognostic marker for HNSCC." (PMID 37643007, 2023).
liver cancer (2 papers, 2022). An epithelial or non-epithelial malignant neoplasm that arises from the liver. "Our data revealed that the expression level of PCIF1 mRNA was significantly elevated in tumor tissues compared with their corresponding non-tumor tissues in various human cancers, including gastric, colorectal, and liver cancers." (PMID 35597784, 2022).
cervical squamous cell carcinoma (1 paper, 2021). A squamous cell carcinoma arising from the cervical epithelium. "Interestingly, there is a correlation between highly expressed PCIF1 and poorer DSS of cervical squamous cell carcinoma and endocervical adenocarcinoma (CESC) (p = 0.0012) and COAD (p = 0.0482)." (PMID 34888238, 2021).
cholangiocarcinoma (1 paper, 2023). A carcinoma that arises from the intrahepatic biliary tree (intrahepatic cholangiocarcinoma) or from the junction, or adjacent to the junction, of the right and left hepatic ducts (hilar cholangiocarcinoma). "The chromatin immunoprecipitation–sequencing results suggested that in cholangiocarcinoma, six genes including PCIF1 were likely to be transcriptionally regulated by YY1." (PMID 39524541, 2023). "However, another study showed that the knockdown of YY1 in cholangiocarcinoma cell lines CCLP1 and RBE resulted in a decrease in PCIF1 expression at both the translational and transcriptional levels." (PMID 39524541, 2023).
endometrial carcinoma (1 paper, 2021). A malignant tumor arising from the epithelium that lines the cavity of the uterine body. "The highest mutation frequency (3.07%) of PCIF1 appeared in endometrial carcinoma." (PMID 34888238, 2021).
lung adenocarcinoma (1 paper, 2021). A carcinoma that arises from the lung and is characterized by the presence of malignant glandular epithelial cells. "PCIF1 phosphorylation of the T158 locus was elevated in normal tissues compared with lung adenocarcinoma tissues; PCIF1 phosphorylation of the S116 locus had no statistical difference between the two groups." (PMID 34888238, 2021).
lung squamous cell carcinoma (1 paper, 2021). "The expression of PCIF1 was positively correlated with MSI of KICH, KIRC, LIHC, and lung squamous cell carcinoma (LUSC) but negatively correlated with MSI of rectum adenocarcinoma (READ) (p < 0.05)." (PMID 34888238, 2021).
osteoporosis (1 paper, 2026). A condition of reduced bone mass, with decreased cortical thickness and a decrease in the number and size of the trabeculae of cancellous bone (but normal chemical composition), resulting in increased fracture incidence. "Additionally, the WNT agonist attenuates the osteoporosis-like phenotype induced by Pcif1 deletion." (PMID 41941537, 2026).
pancreatic adenocarcinoma (1 paper, 2021). "Violin plots showed that the difference expression of PCIF1 had statistical significance in each pathological stages of COAD, KICH, kidney renal clear cell carcinoma (KIRC), liver hepatocellular carcinoma (LIHC), pancreatic adenocarcinoma (PAAD), and skin cutaneous melanoma (SKCM)." (PMID 34888238, 2021).
renal cell carcinoma (1 paper, 2024). "In conclusion, our study identified PCIF1 as a significant epigenetic regulator that promotes the progression of renal cell carcinoma." (PMID 39422663, 2024). "This study explores the oncogenic role of m6Am and its ‘writer’ enzyme, PCIF1, in renal cell carcinoma." (PMID 39422663, 2024).
renal clear cell carcinoma (1 paper, 2023). "High PCIF1 expression exhibited a positive correlation with CD4+ T cell infiltration specifically in renal clear cell carcinoma." (PMID 38162499, 2023).
Sepsis (1 paper, 2022). Sepsis is defined as life-threatening organ dysfunction caused by a dysregulated host response to infection. "In the second sepsis datasets, four diseases including sepsis at 1 day and 3 days and sepsis plus shock at 0 day and 7 days shared one RNA methyltransferase PCIF1 and one RNA methylation reader IGF2BP3." (PMID 35211628, 2022).
stomach tumor (1 paper, 2022). "The upregulation of PCIF1 in stomach tumor tissues is an independent predictor for poor prognosis." (PMID 35597784, 2022).
tumor (15 papers, 2021 to 2026). "Pcif1 deficiency also potentiates the efficacy of anti-PD-1 therapy and improves tumor control in CAR-T cell models, with clinical data linking low PCIF1 expression to superior immunotherapy outcomes." (PMID 41424859, 2026). "Histopathological evaluation revealed that tumours in the combination group were of lower histological grade and exhibited less invasive characteristics, suggesting that PCIF1 deficiency enhances the tumour‐suppressive effects of PD1 blockade." (PMID 40156159, 2025). "The expression of PCIF1 and MTF2 in tumour tissues was consistent with these findings: PCIF1 loss decreased PCIF1+ cell populations, whereas MTF2 loss increased MTF2+ cells." (PMID 40156159, 2025). "Several studies have shown that PCIF1 is clearly associated with tumor, viral, and endocrine diseases." (PMID 37779183, 2023). "Besides, in the SYSUCC cohort, the elevated PCIF1 expression was associated with higher tumour grades and more advanced clinical stages." (PMID 40156159, 2025). "Deletion of Pcif1, either systemically or specifically in T cells, not only reduces tumor burden but also increases the infiltration of activated cytotoxic CD8+ T cells." (PMID 41424859, 2026). "In comparison to anti‐PD1 monotherapy, the combination of PCIF1 knockout with anti‐PD1 treatment significantly reduced tumour burden, as evidenced by decreased lesion area and a reduced number of tumour lesions." (PMID 40156159, 2025). "For instance, recent studies have shown that PCIF1‐mediated m6Am modification selectively inhibits mRNA translation of tumour suppressors, leading to enhanced cell proliferation and metastasis." (PMID 40156159, 2025). "Immunohistochemical analysis of xenograft tumours demonstrated significantly lower expression of PCIF1 and Ki67 in the PCIF1‐knockdown group, indicating reduced cell proliferation." (PMID 40156159, 2025). "Histological analysis at Week 26 revealed that PCIF1 knockout significantly reduced tumour lesion size and incidence, suggesting its critical role in tumour initiation and growth suppression." (PMID 40156159, 2025). "Specifically, higher PCIF1 expression was observed in patients who experienced tumour recurrence and poor response to radiotherapy, as shown by increased IHC scores." (PMID 40156159, 2025). "In contrast, MTF2 knockout led to increased tumour size, whereas the combined knockout of both PCIF1 and MTF2 further exacerbated tumour formation, demonstrating a compensatory oncogenic effect in the absence of MTF2." (PMID 40156159, 2025). "Consistent results were observed in the FAH‐SYSU cohort, with elevated PCIF1 staining in tumour tissues and higher IHC scores compared to normal tissues." (PMID 40156159, 2025). "Mechanistically, immunohistochemical analysis demonstrated that PCIF1 knockout combined with anti‐PD1 treatment not only reduced the proliferation marker Ki67 but also led to a pronounced upregulation of the tumour suppressor MTF2." (PMID 40156159, 2025). "In the SYSUCC cohort, tumour tissues exhibited markedly stronger PCIF1 staining compared to adjacent normal tissues." (PMID 40156159, 2025). "H&E staining confirmed varying levels of tumour invasion across different genotypes, with double‐knockout mice exhibiting more aggressive tumour phenotypes compared to PCIF1 knockout alone." (PMID 40156159, 2025). "This suggests a fine‐tuning mechanism where PCIF1 selectively targets specific tumour suppressors through m6Am methylation." (PMID 40156159, 2025). "Given the emerging role of m6Am in tumour biology, investigating the contribution of PCIF1 to OSCC progression is critical to advancing our understanding of the molecular drivers of this disease." (PMID 40156159, 2025). "In these cancers, PCIF1 overexpression correlates with poor prognosis and increased tumour aggressiveness." (PMID 40156159, 2025).
tumor (continued). "We performed subcutaneously cancer cell injection in nude mice, revealing that PCIF1 silencing significantly inhibits tumor growth, corroborated by reduced staining of the proliferation index marker PCNA." (PMID 39422663, 2024). "Taken together, these data underscore PCIF1's critical functions as an oncogene in tumor progression." (PMID 39422663, 2024). "While signals of in situ foci decreased due to interfered tumor growth, tumor metastasis was nearly eradicated in the PCIF1 knockdown group, highlighting and direct impact of PCIF1 depletion on RCC metastasis." (PMID 39422663, 2024). "To assess PCIF1's role in tumor metastasis in vivo, we orthotopically injected luciferase‐labeled ACHN RCC cells in nude mice." (PMID 39422663, 2024). "The level of PCIF1 in tumor tissue is higher than that adjacent to cancer, indicating that PCIF1 can not only reflect the presence of tumors, but also predict the stage in a dose-dependent manner." (PMID 37779183, 2023). "IHC results demonstrated that PCIF1 expression was mainly localized in the nucleus of tumor cells and that the expression of PCIF1 in HNSCC tissues was significantly higher than that in normal tissues." (PMID 37643007, 2023). "The specific mechanism of PCIF1 in tumors in the future and how it affects the tumor microenvironment need further study." (PMID 37779183, 2023). "Statistically significant correlations were observed between PCIF1-high character and T classification, tumor stage, tumor grade, and lymph node metastasis status." (PMID 37643007, 2023). "At present, there are only a few research-type articles indicating that PCIF1 has a clear correlation with tumor proliferation and development, and the physiological function of PCIF1 still needs further exploration." (PMID 37779183, 2023). "Many studies have shown that PCIF1 plays an important role in tumors and other diseases, and PCIF1 is related to tumor immunity and immunotherapy." (PMID 37779183, 2023). "After inhibiting PCIF1, tumor proliferation, adhesion, migration and other malignant behaviors are improved." (PMID 37779183, 2023). "More importantly, the oncogenic effect was also confirmed in GC patient-derived xenografts, where PCIF1 silencing decreased tumor volume and inhibited lung metastases." (PMID 36768600, 2023). "The migration and invasion of the tumor can be prevented as well as the growth of the tumor and lung metastasis if PCIF1 expression is suppressed." (PMID 37779183, 2023). "To distinguish which immune cells mediate the tumor suppression effect of PCIF1 KO cells, we conducted NK cell and mononuclear MDSC cell consumption on CT26 cells." (PMID 37779183, 2023). "This indicates that PCIF1 knockout enhances the sensitivity of PD-1 and enhances its tumor killing ability." (PMID 37779183, 2023). "PCIF1 KO has an impact on the tumor microenvironment, manifested by an increase in NK cells and a decrease in M-MDSCs, which also has an impact on immunotherapy." (PMID 37779183, 2023). "Currently, there is little research on PCIF1 and immunity, but only a few articles have shown that PCIF1 plays an important role in tumor immunity and immunotherapy." (PMID 37779183, 2023). "Both PCIF1 knockout and PD-1 therapy can inhibit tumor growth, but when combined, the tumor is almost completely eliminated." (PMID 37779183, 2023). "The first indication of the role of m6Am in cancer came from a functional RNAi screening performed in human bladder cancer cells and xenograft mice that identified PCIF1 as a novel tumor suppressor." (PMID 36768600, 2023). "Immunohistochemical staining showed that PCIF1 protein was also significantly raised in tumor tissues form patients with T4 stage compared to that of T1 stage." (PMID 35597784, 2022). "Subcutaneous implantation analysis of cancer cells in nude mice showed that knockdown of PCIF1 in GCSR1 cells obviously suppressed tumor growth compared with control cells." (PMID 35597784, 2022).
tumor (continued). "By reducing tumour burden, PCIF1 depletion may help shift the TME towards a state that is more permissive to immune attack, thereby enhancing PD‐1 blockade efficacy." (PMID 40156159, 2025). "Similarly, the FAH‐SYSU cohort demonstrated consistent findings, with higher PCIF1 levels correlating with aggressive tumour characteristics, such as advanced grade, reinforcing the role of PCIF1 in promoting OSCC progression." (PMID 40156159, 2025). "Conversely, PCIF1 is frequently downregulated in gliomas and acts as a tumor suppressor." (PMID 41446042, 2025). "IHC analyses showed that PCIF1 deletion was associated with reduced expression of Ki67, a proliferation marker, whereas MTF2 deletion increased Ki67 expression, highlighting MTF2's tumour‐suppressive role." (PMID 40156159, 2025). "Specifically, PCIF1 knockout in our mouse models significantly reduced tumour incidence, supporting the notion that inhibiting PCIF1 could offer therapeutic benefits by restoring MTF2 function." (PMID 40156159, 2025). "Regarding tumor regulation, PCIF1 exhibits a context-dependent dual function." (PMID 41446042, 2025). "In vivo experiments further supported the tumour‐promoting role of PCIF1." (PMID 40156159, 2025). "Lastly, a more comprehensive analysis of the tumour immune microenvironment using scRNA‐seq or multiplex IHC could provide deeper insights into PCIF1's broader role in tumour progression." (PMID 40156159, 2025). "Conversely, stable PCIF1 overexpression showed an opposite effect on tumor growth." (PMID 39422663, 2024). "More interestingly, PCIF1 also has a certain effect on the tumor microenvironment." (PMID 37779183, 2023). "We speculate that PCIF1 can play an important role as a tumor biomarker and therapeutic target in the future." (PMID 37779183, 2023). "In PCIF1 KO tumors, the immune cells in the tumor microenvironment changed, indicating that PCIF1 may be used as a therapeutic target for ICB in the future." (PMID 37779183, 2023). "Thus, we provided a primary investigation of the function of PCIF1 in tumor and immune infiltration, accompanied by limitations of this study which can only be solved by experiments." (PMID 34888238, 2021). "Additionally, we conducted total protein expression distribution of the PCIF1 among primary tumor and normal tissues from clinical proteomic tumor analysis consortium (CPTAC) dataset." (PMID 34888238, 2021). "Moreover, we investigated whether PCIF1 knockout could potentiate the therapeutic efficacy of anti‐PD1 immunotherapy by alleviating tumour aggressiveness, offering a novel approach to enhancing immunotherapy response." (PMID 40156159, 2025). "Furthermore, the in vivo subcutaneous tumor implantation model showed that intratumor injection of XY‐14 efficiently counteracted the stimulative effect of PCIF1 overexpression on tumor growth, highlighting the potential of targeting LPP3 with its inhibitor in RCC treatment." (PMID 39422663, 2024). "Concordantly, while sunitinib treatment could effectively inhibit tumor growth in the control groups, the PCIF1 knockdown group exhibited a superior response to treatment reflected in tumor weight and size, accompanied by a significantly decreased staining of PCNA and angiogenesis marker CD31." (PMID 39422663, 2024). "Moreover, targeting PCIF1 leads to a decrease in malignant tumor behavior." (PMID 37779183, 2023). "Moreover, PCIF1 may be related to the tumor microenvironment, immune cell typing, and programmed cell death protein 1(PD-1) drug resistance." (PMID 37779183, 2023). "Clinical analyses further reveal that high PCIF1 expression and low MTF2 expression correlate with advanced tumour stage, poor treatment response and decreased overall survival." (PMID 40156159, 2025). "Together, these findings demonstrate that PCIF1 depletion and PD1 inhibition act through complementary but mechanistically distinct pathways to suppress tumour growth." (PMID 40156159, 2025).